IGFBP3 (insulin like growth factor binding protein 3)
Diseases named in the same sentence as IGFBP3 in open-access papers (continued):
Sharing a sentence is not in itself a finding about the gene and the disease.
breast carcinoma (continued). "Contrary to our expectations, the associations of intact and total IGFBP-3 levels with breast density do not seem to mirror the IGFBP-3-breast cancer associations in the study of Rinaldi and colleagues." (PMID 18471292, 2008). "Our study confirms the previously reported findings with circulating IGFBP-3 levels, but neither the polymorphism (within Block 3 of IGFBP3 gene) nor the haplotype block were associated with breast cancer risk in our data." (PMID 18596909, 2008). "In contrast, associations of levels of total (intact and fragmented) IGF-binding protein-3 (IGFBP-3), the main binding protein of circulating IGF-I, with risk of breast cancer are conflicting and range from a protective association in some studies to an elevated risk in others." (PMID 18471292, 2008). "To comprehensively examine the role of common genetic variation in the IGF1, IGFBP1, and IGFBP3 genes in relation to circulating IGF-I and IGFBP-3 levels and breast cancer risk, we conducted a haplotype-based analysis in the NCI Breast and Prostate Cancer Cohort Consortium (BPC3)." (PMID 18596909, 2008). "In the present study we evaluated the expression level of the IGFBP3 gene in breast tissues from patients with breast cancer or BBD, and investigated potential associations between IGFBP3 mRNA expression levels and the clinicopathologic features of the tumors and breast cancer survival." (PMID 17210081, 2007). "Several but not all previous studies have shown that a high tissue level of IGFBP-3 is related to unfavorable prognostic factors of breast cancer, such as large tumor size, elevated S-phase fraction, elevated DNA aneuploidy, and low levels of ER or progesterone receptor." (PMID 17210081, 2007). "There were no apparent associations of IGFBP3 expression in cancer tissues with either overall survival or disease-free survival in a cohort of 521 patients with breast cancer." (PMID 17210081, 2007). "Our findings increase our understanding of the mechanisms of IGFBP-3 in the pathogenesis of breast cancer and suggest the need for further molecular genetic studies to elucidate the biological significance of the abnormal expression of IGFBP3 in breast lesions." (PMID 17210081, 2007). "In addition, IGFBP-3 has been shown to directly inhibit cell growth and induce apoptosis of breast cancer cells independently of its effect on IGF-I." (PMID 15756268, 2005). "IGFBP-3 regulates breast cancer epithelial growth through IGF-dependent and IGF-independent pathways that involve both growth inhibition and enhanced apoptosis with the potential to switch to growth stimulatory pathways interacting with EGFR, HER-2 and fibronectin." (PMID 15642160, 2005). "Premenopausal women in the top vs bottom third of serum IGF-I concentration had a nonsignificantly increased risk for breast cancer after adjustment for IGFBP-3 (odds ratio (OR) 1.71; 95% confidence interval (CI): 0.74–3.95; test for linear trend, P=0.21)." (PMID 15756268, 2005). "Circulating IGFBP-3 may avert breast cancer development, with the clinical paradox that increasing IGFBP-3 levels in breast tumours may indicate adverse prognostic cancers." (PMID 15642160, 2005). "In this study we looked at the effects of IGFBP-3 on cell growth and death in the normal breast epithelial cell line, MCF-10A and compared the effects of TGF-β on the growth, death and the production of IGFBP-3 in these cells to that in the Hs578T breast cancer cell line." (PMID 12085194, 2002). "Our study found a correlation between the C allele of IGFBP-3 A-202C (SNP rs2854744) with circulating IGFBP-3 levels (rs = 0.164, p = 0.003), in which its serum levels were associated with an increased risk of breast cancer (OR = 1.154; 95%CI 0.982, 1.357, p < 0.25) (data not shown)." (PMID 40493660, 2025). "Also, IGFBP-3 activates Caspase-8 cleavage and induce apoptosis in breast cancer." (PMID 39272080, 2024).
breast carcinoma (continued). "However, GPER1 can activate additional mediators of cell survival, such as extracellular signal-related kinase 1 and 2 (ERK1/2), ELK1, CREB, and FOS that may be involved in IGFBP-3 induction upon Ful treatment in breast cancer cells." (PMID 39619437, 2024). "IGFBP-3 may play a role in the pathophysiology of prostate, lung, and breast cancer." (PMID 37510722, 2023). "However, an observational and Mendelian randomization analysis from the UK Biobank found that IGFBP3 concentrations were not related to the risk of breast cancer (OR = 1.00)." (PMID 36660244, 2023). "Besides, insulin-like growth factor binding protein 3 (IGFBP-3) could inhibit cell proliferation and promote cell apoptosis by regulating local IGF-1 concentration and the anti-apoptosis effect of IGFBP-3 can be inhibited in breast cancer cells." (PMID 35096970, 2021). "Thus, IGFBP-3 may represent a novel predictor of and potential therapeutic target for triple-negative premenopuasal breast cancer." (PMID 33859244, 2021). "IGFBP-3 could increase cell growth in breast cancer cells in an IGF-independent manner." (PMID 32478064, 2020). "Treatment of recombinant IGFBP-3 protein to breast cancer cells could inhibit cell growth." (PMID 32478064, 2020). "There are fewer data on biomarkers for women at elevated breast cancer risk; these results suggest that elevated levels of IGF-1 and IGFBP-3 may be similarly related to breast cancer risk on a relative scale irrespective of absolute baseline risk." (PMID 33092613, 2020). "A meta-analysis of 21 case-control studies including 3,609 cases and 7,137 controls has found that high concentrations of IGF1 and IGFBP3 were associated with an increased risk of incident breast cancer among premenopausal women but not among postmenopausal women." (PMID 32974138, 2020). "Moreover, breast cancer patients with poor diagnosis overexpress IGFBP3 at mRNA and protein levels." (PMID 31220095, 2019). "The association between IGFBP3 with epidermal growth factor receptor (EGFR), another breast cancer-related gene, may contribute to tumorigenesis in a manner similar to the long-range interactions between IGFBP3 and breast carcinoma amplified sequence (BCAS1-4) in MCF7 cells." (PMID 29149895, 2017). "Interestingly, the authors reported an association between changes in IGFBP-3 and physical functioning, suggesting a link between changes in IGF binding proteins and some domains of quality of life in breast cancer survivors, although these associations warrant additional research." (PMID 27562357, 2016). "In addition, regulation of IGF-I/Akt survival signalling may function as a key point of convergence that may determine breast cancer cell fate in response to 1, 25-D3/IGFBP-3." (PMID 23690781, 2013). "In addition, IGFBP3 also promotes migration in breast cancer cells." (PMID 24039934, 2013). "Moreover, fragmented or total IGFBP-3 levels were negatively associated with mammographic breast density, one of the strongest known breast cancer risk factors, whereas no such association was seen with intact IGFBP-3." (PMID 18471292, 2008). "BCAC also analyzed data from 12 studies for 16 SNPs in various candidate genes and concluded that only 5 SNPS (CASP8 D302H, IGFBP3-202 c > a, PGRV660L, SOD2 V16A, and TGFB1 L10P) were associated with breast cancer, but the statistical significance of the association was only borderline." (PMID 21655367, 2008). "Studies have shown an association of increased serum levels of IGF-I and decreased levels of IGFBP-3 with an increased risk of breast cancer in premenopausal women, suggesting that these patients may benefit from measures able to reduce serum IGF-I levels and increase IGFBP-3 levels." (PMID 17645796, 2007). "It has been suggested that IGFBP-3 may also have an IGF-independent growth inhibitory effect on breast cancer cells, and it is important to evaluate tumor tissue specific expressions of IGFBP3 level to understand the role of this protein in breast tumorigenesis." (PMID 17210081, 2007).
breast carcinoma (continued). "IGFBP-3 also exhibits IGF-independent effects, such as inhibiting cell growth and inducing apoptosis, and can interact with breast cancer in both stimulatory and inhibitory manners." (PMID 40493660, 2025). "Studies have shown that IGFBP-3 and IGF-1 levels are related to the development and recurrence of breast cancer." (PMID 40493660, 2025). "Other reports indicate that IGFBP-3 binds to GPR78 to stimulate autophagy, thus promoting survival in ERα positive breast cancer cells." (PMID 39619437, 2024). "Exercise program alone in breast cancer patients also found improvements in IGF-1, IGFBP-1 and IGFBP-3 in maintenance of BMD." (PMID 36839371, 2023). "A similar relationship has been reported with IGFBP‐3 and GRP78, where the combination of low GRP78 and high IGFBP‐3 was clinically significant, indicating poorer overall survival of breast cancer patients." (PMID 37212470, 2023). "The ability of IGFBP‐3 to differentially affect cell survival and invasion, depending upon the extracellular environment, is influenced by the presence of GRP78 in human breast cancer cell lines." (PMID 37212470, 2023). "In this study, we aimed to show that IGFBP-3 induces cellular senescence via suppression of the telomerase activity, thereby inhibiting MCF-7 breast cancer cell proliferation." (PMID 37253773, 2023). "Moreover, high IGFBP-3 levels may have a protective effect against breast cancer." (PMID 35356065, 2022). "Most existing studies on the effects of exercise on inflammatory factors and IGF systems in breast cancer survivors examine IL-6, IL-10, IL-1β, TNF-α, CRP, IGF-1, and IGFBP-3 levels." (PMID 36482346, 2022). "Similar to insulin-like growth factor binding protein 3 (IGFBP3), IGFBP7 can either act as a tumor promoter or suppressor in many different cancer types, including breast cancer, but the reason for this dual-action remains to be elucidated." (PMID 34606580, 2021). "In this subset of genes, we confirmed three genes with established roles in breast cancer, including HES4, CCND1, IGFBP3, with quantitative RT-PCR analyses." (PMID 31462705, 2020). "It should be noted that there are concentration-dependent effects of IGFBP-3 on cell proliferation observed in breast cancer cells, additionally, TGF-β has been demonstrated to inhibit or augment IGFBP-3 production in a cell line specific manner." (PMID 32478064, 2020). "While AMF/PGI, which is a tumor-secreted cytokine, is endocytosed and regulates cell migration, proliferation, and survival, IGFBP-3 has been shown to inhibit AMF/PGI-induced cell migration in T47D and MCF-7 breast cancer cells." (PMID 32443727, 2020). "Interaction of IGFBP-3 and GRP78 has been identified in human breast cancer cells using a yeast two-hybrid screening." (PMID 32443727, 2020). "With breast cancer cells we showed that knock-down of GRP78 negated the entry of IGFBP-3 into the cells and this switched the action of IGFBP-3 from promoting to inhibiting cell death." (PMID 33352865, 2020). "Numerous studies have provided evidence that IGFBP3 and IGFBP7 are involved in a variety of cancers, including hepatocellular carcinoma (HCC), breast cancer, gastroesophageal cancer, colon cancer, prostate cancer, among many others." (PMID 32500027, 2020). "Inhibition of growth by IGFBP-3 and PPAR-Υ was higher than either alone in MCF-7, MDA-MB-231, MDA-MB-468 breast cancer cells." (PMID 32478064, 2020). "Several growth factor–related breast cancer genes (EGF, IGF1, IGF1R, IGF2, IGFBP3, IL10, TGFB1, and VEGF), including 26 SNPs, were used as simulation data to evaluate existing algorithms and the proposed HTGA." (PMID 32554381, 2020).
breast carcinoma (continued). "A randomized controlled trial of postmenopausal breast cancer survivors found that aerobic exercise decreased IGF-1 and insulin-like growth factor-binding protein-3 (IGFBP-3), a predominant binding protein for IGF-1." (PMID 31816813, 2019). "Moderate-intensity aerobic exercise, per week, used in the study is proved to be tolerated in breast cancer survivors and efficacious in decreasing levels of IGF-I and IGFBP-3." (PMID 31759342, 2019). "Our results suggest that the known variants in the genes of the IGF-1 axis play minor roles in the timing of elevation of IGF-1 and IGFBP-3 protein levels during puberty, similar to the role that SNPs in IGF-1 axis genes play in breast cancer." (PMID 30249230, 2018). "IGFBP1 and IGFBP3 genes are located adjacent to each other and are important regulators of bioavailability of IGF-1, which stimulates proliferation of breast cancer cell lines and primary culture." (PMID 30400783, 2018). "In 2008 serum levels of tissue polypeptide-specific antigen, breast cancer-specific cancer antigen 15.3 (CA15–3), and insulin-like growth factor binding protein-3 (IGFBP-3) were introduced as predictors on a logistic regression." (PMID 29301500, 2018). "We first analyzed the level of secreted IGFBP3 and cellular IGFBP3 in MCF-7 and MTA1 overexpressing breast cancer cells." (PMID 28393842, 2017). "At the molecular level, IGFBP3 activated SphK1 and led to S1P-dependent transactivation of EGFR in normal mammary epithelial and breast cancer cells." (PMID 29108245, 2017). "The long-range interactions of insulin-like growth factor-binding protein 3 (IGFBP3), a key gene in the development of breast cancer, are increased in breast cancer cells relative to those in normal cells." (PMID 29149895, 2017). "In a study using the EZH2 inhibitor 3-deazaneplanocin A (DZNep), it was found that its treatment depleted breast carcinoma cells of the PRC2 complex members (EZH2, SUZ12, and EED),and subsequently reactivated expression of IGFBP-3." (PMID 28042859, 2016). "IGFBP-3-dependent breast cancer cell chemoresistance, while contrary to studies in some other cancers showing IGFBP-3-dependent chemosensitivity, might in part explain the association between high IGFBP-3 (and EGFR) expression and poor patient outcomes in women with ER-negative breast cancer." (PMID 26221601, 2015). "Insulin-like growth factor (IGF) binding protein 3 (IGFBP3) is a major carrier of IGF1 and IGF2 in circulation and IGFBP3 levels are reduced in breast cancer patients, giving rise to higher free IGF1 levels and poor prognosis." (PMID 24534923, 2014). "Breast cancer proliferative genes, such as aurora kinase, ERCC1, IGFBP3 were inhibited and growth inhibitory genes, such as NQO1, PTPRJ were activated by GTx-027." (PMID 25072326, 2014). "In this study the role of IGF binding protein-3 (IGFBP-3) in 1, 25-D3-induced apoptosis was investigated using parental MCF-7 breast cancer cells and MCF-7/VDR cells, which are resistant to the growth inhibitory effects of 1, 25-D3." (PMID 23690781, 2013). "In this study, we used IGFBP3, a gene involved in breast cancer pathogenesis, as bait in a 4C-seq experiment comparing normal breast cells (HMEC) with two breast cancer cell lines (MCF7, an ER positive cell line, and MDA-MB-231, a triple negative cell line)." (PMID 24019942, 2013). "To examine this long-range interaction in more detail, we labeled gene pairs EGFR and IGFBP3 by 3D-FISH in HMEC and breast cancer cell lines MCF7 and MDA-MB-231." (PMID 24019942, 2013). "This analysis included 6,912 breast cancer cases and 8,891 matched controls (n = 6,410 for circulating IGF-I and 6,275 for circulating IGFBP-3 analyses) comprised primarily of Caucasian women drawn from six large cohorts." (PMID 18596909, 2008).
breast carcinoma (continued). "Breast cancer cells secrete various types of IGFBP, and the expression of IGFBP-3 is hormonally regulated." (PMID 17210081, 2007). "Breast cancer cells typically express several IGFBPs, with IGFBP-2, IGFBP-3, IGFBP-4 and IGFBP-5 being observed most often." (PMID 15642160, 2005). "Growth inhibition by IGFBP-3 has been reported in many cell lines such as Hs578T and MCF-7 breast cancer cells." (PMID 12085194, 2002). "TGF-β-induced growth inhibition seen in Hs578T breast cancer cells, as well as the TGF-β-induced proliferation seen in colon cancer cells and human airway smooth muscle cells is at least partially mediated by IGFBP-3." (PMID 12085194, 2002). "In the IGF unresponsive breast cancer cell line, Hs578T and the IGF-responsive normal breast epithelial cell line, MCF-10A, IGFBP-3 can inhibit cell growth." (PMID 12085194, 2002). "Breast cancer treatment increases body fat, blood lipids, IGFBP-3, negative impact on sexual functioning such as vulvo-vaginal atrophy, and decreases the activation of natural killer cells." (PMID 39156757, 2024). "IGFBP-3 was also induced by Tam in all cell lines tested, suggesting that these Ful and Tam may have a common mechanism of IGFBP-3 induction in breast cancer cells." (PMID 39619437, 2024). "One additional modulator of IGFBP-3 is microRNA 34 (miR34), which was recently shown to downregulate IGFBP-3 in human lung epithelial cells and may have a role in IGFBP-3 regulation in breast cancer epithelial cells." (PMID 39619437, 2024). "While IGFBP-3 is clearly an important modulator of breast cancer, mechanisms of breast cancer cell modulation by IGFBP-3 are not adequately understood." (PMID 39619437, 2024). "Our previous study demonstrated that IGFBP-3 induced G1 cell cycle arrest by inhibiting cyclin D1, cyclin D3, cyclin E, cyclin A, CDK2, CDK4, total and phospho-pRb, and increasing p21 and p16 in MCF-7 breast cancer cells." (PMID 37253773, 2023). "We observed interactions of TGFB1 and IGFBP‐3 gene expression with a family history of breast cancer (data not shown)." (PMID 35304837, 2022). "Meanwhile, IGFBP3 competitively bound to GRP78 and disassociated GRP78 from Caspase-7, leading to enhanced production of activated Caspase-7 and the following apoptosis in breast cancer." (PMID 35871161, 2022). "Moreover, IGFBP-3 has been shown to bind to and activate TGF-β receptor, thus leading to phosphorylation of Smad2 and Smad3 in breast cancer cells." (PMID 35798794, 2022). "Meanwhile, postoperative changes in IGF-I, IGFBP-3, IGFBP-7, or IGF-I/IGFBP-3 molar ratios were not prognostic indicators of breast cancer recurrence once treatment was taken into account." (PMID 33767994, 2021). "The overall association between IGF-1 or IGFBP-3 elevation (≥ median in controls) and breast cancer risk was elevated, but not statistically significant (IGF-1 OR = 1.37, 95% CI = 0.66–2.85; IGFBP-3 OR = 1.62, 95% CI = 0.81–3.24)." (PMID 33092613, 2020). "No other significant associations with all-cause mortality, breast cancer-specific mortality, and breast cancer recurrence were observed for IGFBP3, IGF1/IGFBP3 ratio, insulin, and C-peptide." (PMID 32974138, 2020). "Additionally, we performed IHC on 69 formalin-fixed, paraffin-embedded breast cancer sections to assess levels and localisation of GRP78 and IGFBP-3." (PMID 33352865, 2020). "Indeed, EA acted as a potent anti-estrogenic agent in the oestrogen-sensitive human breast cancer MCF-7 cells, increasing insulin-like growth factor-binding protein 3 (IGFBP-3) levels, whose production is usually inhibited by oestrogens." (PMID 30441769, 2018). "In breast cancer, the significance of nuclear IGFBP-3, both functionally and as a biomarker, is not fully understood." (PMID 29623068, 2018). "IGFBP3 also failed to discriminate cases from controls, although was decreased in case samples that went on to be diagnosed with HER2+ breast cancer where there was a strong association for the <1.15 years to diagnosis group." (PMID 28081538, 2017).